IRS1 (insulin receptor substrate 1)
Diseases named in the same sentence as IRS1 in open-access papers (continued):
Sharing a sentence is not in itself a finding about the gene and the disease.
Insulin resistance (continued). "It has been reported that agents such as FFAs, cytokines, cellular stress and hyperinsulinemia, induce insulin resistance, and lead to activation of several serine/threonine kinases and phosphorylation of IRS-1 as well." (PMID 19997558, 2009). "Of interest here is the finding that GRK2 mediates endothelin-1-induced insulin resistance via the inhibition of both Gαq/11 and insulin receptor substrate-1 pathways in 3T3-L1 adipocytes." (PMID 20204079, 2009). "Previous studies have shown that increased phosphorylation of mTOR and S6K causes sub-cellular redistribution of IRS-1, and inactivates IRS-1 by increasing its serine phosphorylation leading to insulin resistance." (PMID 19169352, 2009). "In conclusion, we report a specific link between a hyperinsulinemic, hyperandrogenic environment and an elevation of IRS-1 serine phosphorylation of IRS-1, which has been associated with the development of insulin resistance." (PMID 19169352, 2009). "In contrast, we found that high-fat (HF) overfeeding results in a significant increase in serine phosphorylated IRS-1, a traditional determinant of insulin resistance." (PMID 19781106, 2009). "Ability of S6K1 to promote serine phosphorylation of IRS-1 has been suggested as a potential mechanism of insulin resistance." (PMID 19781106, 2009). "In cultured cells, TNF-αinduces insulin resistance through increased serine phosphorylationof insulin receptor substrate-1 (IRS-1), which subsequently convertsIRS-1 to an inhibitor of insulin receptor tyrosinekinase activity." (PMID 19148295, 2008). "Genetic variance in the IRS-1 is thought to play a key role in the insulin resistance that characterizes type 2 diabetes." (PMID 20300294, 2008). "Such treatment has been shown to inhibit insulin receptor substrate -1 (IRS-1) expression and activation thereby inducing insulin resistance." (PMID 18549505, 2008). "These mice show reduced adiposity similar to CR and FIRKO mice; however, Irs1-/- mice show moderate insulin resistance." (PMID 19412415, 2007). "Tyrosine phosphorylation of IRS-1 enhances insulin sensitivity, whereas serine phosphorylation of IRS-1 by S6 kinase induces insulin resistance." (PMID 19412415, 2007). "Prolonged signal transduction via phosphoinositide 3-kinase (PI3K), which generates the lipid second messenger phosphatidylinositol 3,4,5-trisphosphate, has been shown to induce a state of insulin resistance in cells, in part through degradation of IRS-1." (PMID 15522123, 2004). "Furthermore, insulin receptor substrate-1 (IRS-1) proteins become less active due to the development of hyperinsulinemia, which arises from insulin resistance as a result of the reduced expression of insulin receptors (IR)." (PMID 41169480, 2025). "A 2-year RCT comparing the effects of energy-restricted diets on body weight in overweight and obese subjects reported a significant interaction between IRS1 rs2943641 genotype and dietary groups on changes in weight, insulin resistance, and HOMA-IR after adjustment for covariates." (PMID 40732974, 2025). "Among the six mammalian IRS proteins (IRS-1, IRS-2, IRS-3, IRS-4, IRS-5, IRS-6), IRS-1 and IRS-2 are typically considered key nodes in the insulin signaling system, closely associated with the development of insulin resistance." (PMID 39966707, 2025). "TNF-α and IL-6 may cause insulin resistance by suppressing the expression of GLUT-4 and insulin receptor substrate-1 (IRS-1) and activating the NF-κβ pathway." (PMID 40541974, 2025). "Therefore, brain insulin resistance comes from the downregulation of IR or an incorrect activation of the insulin signaling cascade, mainly driven by IRS-1 inhibition." (PMID 40362446, 2025). "Besides the regulation in lipid metabolism, IRS1 was validated as a key regulator of glucose metabolism and insulin resistance." (PMID 41410190, 2025).
Insulin resistance (continued). "Oral administration of EnP at a dose of 75 mg/kg body weight reduced fasting blood glucose levels, improved oral glucose tolerance, alleviated insulin resistance, and mitigated hepatic insulin resistance by modulating the IRS1/PI3K and JNK signaling pathways in type 2 diabetic mice." (PMID 40552121, 2025). "Among the four mammalian IRS proteins (IRS-1, IRS-2, IRS-3, IRS-4), IRS-1 and IRS-2 are considered key nodes in the insulin signaling system, and their dysfunction is closely linked to the development of insulin resistance." (PMID 39966707, 2025). "MSTN may induce insulin resistance by degrading insulin receptor substrate 1 (IRS1) through the E3 ubiquitin ligase Cbl proto‐oncogene B (Cblb) in a Smad3‐dependent manner." (PMID 41190649, 2025). "Since the presence of IRS-3 compensates for the absence of IRS-1, MG53-mediated degradation of IRS-1 is unlikely to cause insulin resistance." (PMID 40282872, 2025). "The results indicated that QHTTF could enhance the expression of IRS-1 and GLUT4 proteins in the pancreas to some extent, which may be associated with an improvement in insulin resistance." (PMID 41011216, 2025). "Mechanistically, this central insulin resistance was associated with reduced protein levels of the p110β subunit of phosphoinositide 3-kinase (PI3K) and enhanced serine phosphorylation of insulin receptor substrate-1 (IRS-1) in the hypothalamic arcuate nucleus (ARC)." (PMID 40443735, 2025). "In insulin resistance, IRS-1 is phosphorylated on Ser307 instead of activating Tyr phosphorylation." (PMID 40430434, 2025). "Mechanistically, angiotensin II and endothelin-1 directly inhibited insulin receptor substrate-1 phosphorylation, promoting systemic insulin resistance, while hyperinsulinemia stimulated vascular smooth muscle cell proliferation and endothelin-1 secretion, further increasing vascular resistance." (PMID 40022080, 2025). "Following intervention with DP, there was a partial recovery in the levels of IRS1 and PI3K proteins, indicating that DP might ameliorate hepatic insulin resistance by stimulating the IRS1/PI3K signaling pathway." (PMID 40565724, 2025). "Moreover, ferulic acid derived from Hibiscus mutabilis mitigates fatty acid-induced insulin resistance by restoring insulin receptor expression, possibly via the upregulation of insulin receptor substrate-1 (IRS)-1." (PMID 40565007, 2025). "A study also points to TRF’s ability to improve insulin resistance in a diabetic animal model via the insulin receptor substrate 1 (IRS-1) and AMP-activated protein kinase/ Sirtuin 1/ Peroxisome proliferator-activated receptor-γ coactivator 1-α (AMPK/SIRT1/PGC1α) pathways." (PMID 38916919, 2025). "ASOs modulating IRS1 expression may be possible to restore proper insulin signaling and reduce insulin resistance, improving the metabolic state of the patient." (PMID 39944202, 2025). "A 2024 study demonstrated that adipose tissue insulin resistance is more pronounced in men than women, with men showing 10-fold lower insulin sensitivity and decreased adipose expression of insulin receptor substrate 1 (IRS1)." (PMID 41008585, 2025). "Insulin resistance in skeletal muscle stemming from high FA availability has been causally linked to DAG and ceramide accumulation, resulting in non‐typical PKC isoform activation, and decreased IRS‐1 and AKT activation." (PMID 39487600, 2025). "For instance, progesterone inhibits insulin receptor substrate (IRS‐1) signaling, which may lead to insulin resistance during pregnancy, while estrogen increases GLUT4 translocation in adipocytes and the liver." (PMID 41243426, 2025). "In ovariectomized female rats, the phosphorylation levels of IRS-1 and Akt proteins were significantly reduced, systemic insulin resistance gradually became severe, and fasting hyperglycemia even occurred; these changes would be alleviated if E2 was supplemented in time." (PMID 40647233, 2025).
Insulin resistance (continued). "By targeting IRS-1, IL-1β is capable of impairing insulin signaling and action and could thus participate (in combination with other cytokines) in the development of insulin resistance in adipocytes." (PMID 41012578, 2025). "This study suggested that QHTTF treatment may regulate insulin resistance by upregulating IRS-1 and GLUT4 expression in pancreatic tissues, potentially indicating modulation of the insulin signaling pathway." (PMID 41011216, 2025). "The expression of IRS-1 is significantly reduced in individuals who are obese or insulin-resistant." (PMID 40362446, 2025). "Ectopic lipid accumulation triggers lipotoxicity, which is characterized by the release of FFAs and proinflammatory cytokines that impair insulin signaling by phosphorylating IRS-1 at serine residues; this leads to insulin resistance, which is a primary driver of type 2 DM." (PMID 41438998, 2025). "Furthermore, TNF-α induces serine phosphorylation of insulin receptor substrate-1 (IRS-1), inhibiting the activation of downstream signals, leading to insulin resistance and contributing to EC development." (PMID 41440200, 2025). "Based on network analysis of the top 10 genes, it was hypothesized that JWQZG may alleviate insulin resistance by modulating the expression of IRS1 and AKT." (PMID 40221773, 2025). "Accelerated urbanization and increased consumption of fast food in Southeast Asia could exacerbate insulin resistance through epigenetic mechanisms, such as methylation of the IRS1 gene." (PMID 41262938, 2025). "Moreover, pharmacological disruption of the MG53–IRS1 interaction with small‐molecule inhibitors prevents IRS1 degradation, thereby enhancing insulin signaling in muscle cells and improving glucose homeostasis in animal models of insulin resistance." (PMID 41362701, 2025). "Indeed, TNF-α induces insulin resistance through mechanisms such as increased serine phosphorylation of IRS-1, which impairs insulin receptor tyrosine kinase activity and insulin signal transduction." (PMID 41574186, 2025). "This not only drives the sustained release of pro-inflammatory cytokines (such as IL-1β and TNF-α) but also disrupts insulin signaling through JNK/IRS-1 phosphorylation pathways, forming the pathological basis for chronic low-grade inflammation and insulin resistance." (PMID 40980312, 2025). "For instance, it has been shown that TNFα and other cytokines may also activate PTP1B which has been shown to block the IRS1/2‐dependet activation of AKT thereby subsequently leading to the development of insulin resistance." (PMID 39344016, 2025). "Excessive physiological hypercortisolism may lead to insulin resistance by reducing the insulin receptor substrate 1 (IRS-1) content." (PMID 40362828, 2025). "ECD also resolved hepatic insulin resistance by activating the IRS1-Akt-FoxO1 pathway." (PMID 41304952, 2025). "Since these two modifications may compete for the same or adjacent sites, reduced O‐GlcNAcylation may lift the inhibition on phosphorylation, thereby promoting IRS‐1 phosphorylation, insulin resistance, and further AD development." (PMID 41394960, 2025). "In addition, it has been demonstrated to attenuate insulin resistance of patients with T2D by possibly increasing IRS1 gene expression." (PMID 41294899, 2025). "Notably, ketone bodies themselves contribute to insulin resistance by downregulating cell surface insulin receptors and inhibiting insulin receptor substrate-1 (IRS-1) phosphorylation." (PMID 41010281, 2025). "Functionally, impaired insulin release driven by ABCC8 R653Q may initiate chronic postprandial hyperglycemia, which contributes to insulin resistance through downregulation of IRS1 and the PI3K–Akt pathway." (PMID 40981175, 2025).
Insulin resistance (continued). "Apigenin significantly increases glucose consumption and glycogen synthesis, suppresses the production of ROS and AGEs, and improves insulin resistance in IR-HepG2 cells, and elevated the level of protein expression of IRS-1, IRS-2, PI3K, and p-AKT is observed in IR-HepG2 cells." (PMID 38799166, 2024). "However, in both the bergenin and metformin groups (P < 0.01), ins expression decreased while irs1, irs2a, and irs2b expression increased, indicating bergenin’s effectiveness in alleviating insulin resistance." (PMID 39148536, 2024). "NE has been shown to lead to an exacerbation of insulin resistance via the degradation of insulin receptor substrate 1(IRS1) and a decrease in the abundance of the glucose transporter glucose transporter type 4 gene protein, resulting in diminished glucose uptake." (PMID 38167145, 2024). "Interestingly, IRS1 and 2 levels resulted significantly downregulated in the IR model, while ladarixin was able to counteract this effect, thus ameliorating the insulin resistance condition." (PMID 39627194, 2024). "TNF-α activates T lymphocytes and macrophages, inducing the production of other cytokines and cell adhesion molecules and potentially inducing insulin resistance by reducing insulin signaling and promoting the serine phosphorylation of insulin receptor substrate 1 (IRS1)." (PMID 39408723, 2024). "Diabetic patients often experience insulin resistance (reduced sensitivity of cells to insulin), leading to abnormal insulin signal transduction, including reduced expression and function of insulin receptor substrate-1 (IRS-1) and blocked PI3K/Akt signaling pathway." (PMID 39045049, 2024). "Consequently, exogenous NTs ameliorate insulin resistance in HepG2 cells by modulating the IRS-1/AKT/FOXO1 pathways and regulate glucose consumption, glycogen content, insulin signaling pathways, AMPK activity, oxidative stress, and inflammatory status." (PMID 38931156, 2024). "The two protein molecules interacted with the insulin receptor, and their overexpression negatively regulated an insulin-induced phosphorylation of insulin receptor substrates (IRS, gene name: Irs1 and Irs2), which is one of the most important factors contributing to insulin resistance in the body." (PMID 39063287, 2024). "In the case of HCV infection, the inflammation caused by liver damage and subsequent insulin resistance may contribute to the development of hyperglycaemia, but HCV may directly increase insulin resistance by downregulating insulin receptor substrate-1." (PMID 38374451, 2024). "Insulin resistance in muscle and liver cells appears to be a direct result of the intracellular lipid-induced inhibition of insulin-stimulated insulin receptor substrate (IRS)-1 tyrosine phosphorylation." (PMID 38791525, 2024). "The results demonstrated that GP could improve insulin resistance by promoting glucose uptake and glycogen synthesis and inhibiting gluconeogenesis through regulating the IRS1/PI3K/Akt signaling pathway, which might be a potential alternative therapy for T2DM." (PMID 38921004, 2024). "When IRS1 is knocked out, mice exhibit peripheral insulin resistance and growth retardation." (PMID 39526249, 2024). "Insulin resistance may be due to the activation of Ser/Thr kinases; decreased expression of IRS-1, GLUT4 and PPARγ; or activation of suppressor of cytokine signaling 3 (SOCS3) in adipocytes." (PMID 38397072, 2024). "Additionally, insulin resistance triggers the release of insulin-like growth factor 1 and insulin receptor substrate 1, influencing cell proliferation and apoptosis, contributing to hepatocarcinogenesis." (PMID 38987736, 2024). "These inflammatory cascades further inhibit IRS-1, ultimately leading to insulin resistance." (PMID 38818523, 2024).
Insulin resistance (continued). "Secondly, meat consumption provides substantial amounts of saturated fatty acids, notably palmitic acid, which may inhibit insulin receptor substrate-1, phosphatidylinositol-3-kinase, or protein kinase B in adipocytes, contributing to insulin resistance." (PMID 39106225, 2024). "The results suggest that therapeuticintervention aimed at addressing the interaction between MG53 and insulinreceptor substrate 1 (IRS-1) can be developed, which could serve as a novelstrategy for treating insulin resistance-linked metabolic conditions." (PMID 39077334, 2024). "Similarly, we only assessed one indicator of insulin resistance (pAkt) following insulin stimulation; however, Akt is a target of insulin downstream of IRS1 and PI3K and is regarded as a central node in the proximal insulin signaling cascade." (PMID 39057712, 2024). "The majority of this effect may occur through the inhibition of carbohydrate digestion; however, recent studies have shown that Reducose® can also improve factors contributing to insulin resistance through the promotion of IRS-1 phosphorylation." (PMID 38892603, 2024). "In our hepatic insulin resistant mouse model (hepatic insulin receptor substrate 1 (IRS1) and IRS2 double knockout (DKO)), metformin action on glycemic control was impaired, which is largely improved by further deletion of hepatic TGF-β1 (TKObeta1) or hepatic Foxo1 (TKOfoxo1)." (PMID 38397103, 2024). "However, in the context of insulin resistance, the downstream signaling pathway is suppressed owing to the enhanced phosphorylation of IRS1 serine." (PMID 38921004, 2024). "Notably, this impairment manifests in the disruption of mitochondrial bioenergetics in the brain which precedes the accumulation of well-established markers of insulin resistance, such as inhibited IRS1." (PMID 38843768, 2024). "Furthermore, ER stress induces insulin receptor signaling through the increase in serine phosphorylation and a decrease in tyrosine phosphorylation of IRS-1, leading to insulin resistance." (PMID 38727305, 2024). "We speculate that lower pS307IRS1/total IRS1 leads to more brain insulin resistance and vascular disease, which contribute to the decline of perceptual speed." (PMID 38029396, 2024). "The Western blot analysis further confirmed that CMP could promote the activation of the IRS1/Akt/S6K protein synthesis signaling pathway and reduce insulin resistance." (PMID 38397848, 2024). "Meanwhile, insulin resistance could stimulate the release of insulin‐like growth factor 1 and insulin receptor substrate 1, which may influence cell proliferation and apoptosis." (PMID 37840448, 2024). "Based on our findings, we suggest that increased insulin signaling promotes the expression of CUL1, resulting in the breakdown of IRS1 to turn the signaling off temporarily; however, prolonged overnutrition disrupts IRS1 consistently, leading to the development of insulin resistance." (PMID 38212312, 2024). "Studies have indicated that inflammatory elements can induce insulin resistance through the ikappaB kinase beta (IKKβ)/nuclear factor kappa B (NF-κB)-JNK- insulin receptor substrate-1 (IRS-1)- protein kinase B (AKT) signaling pathway present in the liver and muscles." (PMID 39040602, 2024). "In addition, the increase in the phosphorylation level of these proteins suggested that the insulin resistance alleviation effect of the plant extract is obtained by stimulating the IRS1/PI3K/AKT signaling pathway." (PMID 39795155, 2024). "Furthermore, in response to intracellular and extracellular stresses, the activations of JNK and NF-κB induce insulin resistance through the serine phosphorylation of the insulin receptor substrate (IRS)-1 or IRS-2, subsequently blocking insulin signaling." (PMID 38248467, 2024). "Our findings may suggest an important role of IRS-1 for sex differences in adipose insulin resistance among those with obesity." (PMID 38491191, 2024).